INS (insulin)
Diseases named in the same sentence as INS in open-access papers (continued):
Sharing a sentence is not in itself a finding about the gene and the disease.
pancreatic ductal adenocarcinoma (18 papers, 2007 to 2025). An infiltrating adenocarcinoma that arises from the epithelial cells of the pancreas. "Fibroblast (FGFs) and insulin (IGF) growth factor pathways are among 10 most recurrently altered genomic pathways in pancreatic ductal adenocarcinoma (PDAC)." (PMID 34061869, 2021). "Similar studies in pancreatic ductal carcinoma support a role for altered acetyl-CoA abundance through AKT-ACLY signaling by growth factors including insulin in promoting tumorigenesis." (PMID 31315653, 2019). "Insulin involvement in immune checkpoint regulation boosts PD-L1 expression in pancreatic ductal adenocarcinoma cells through a variety of pathways in the three cell lines studied, including increased InsR-A expression in A818-6 cells and modification of the adaptor protein Gab1 in BxPc3 cells." (PMID 37377916, 2023). "Insulin involvement in immune checkpoint regulation enhances PD-L1 expression in pancreatic ductal adenocarcinoma cells via many routes in the three cell lines studied, including increased InsR-A expression in A818-6 cells and modification of the adaptor protein Gab1 in BxPc3 cells." (PMID 37664033, 2023). "Furthermore, the involvement of insulin in the regulation of immune checkpoints has been investigated, particularly in the context of pancreatic ductal adenocarcinoma cells." (PMID 37780567, 2023). "These experimental studies support a biologic mechanism whereby elevated concentrations of serum insulin may promote the development of pancreatic ductal carcinoma." (PMID 17533398, 2007). "Experimental studies have demonstrated that insulin may have growth-promoting effects on pancreatic ductal adenocarcinoma cells and that peripheral insulin resistance promotes pancreatic ductal carcinogenesis." (PMID 17533398, 2007). "Pancreatic ductal adenocarcinoma (PDAC) is accompanied by endocrine dysfunction, particularly involving dysregulation of the insulin and insulin-like growth factor (IGF) signaling pathways." (PMID 40443651, 2025). "Using pancreatic ductal adenocarcinoma (PDAC)-derived cells, we also revealed that the ATRA induced up-modulation of Vav1 is essential for the retinoid-induced trans-differentiation of neoplastic cells into insulin producing cells." (PMID 33165749, 2021). "MDK, which originated from pancreatic ductal adenocarcinoma cells, exerted deleterious effects on paraneoplastic beta cells by binding to the SDC4 receptor on the beta cell surface and subsequently downregulating the Ras signaling pathway, thereby impairing insulin production and secretion." (PMID 40709672, 2025).
psychological distress (18 papers, 2009 to 2025). "The increased insulin released and brain serotonin concentration after sugary soft drinks are closely linked to emotional dysregulation and later distress." (PMID 40123936, 2025). "After correcting for multiple comparisons, the associations between insulin use, and vitality and general health (SF-36), and those between insulin use and barriers to activity and psychological distress (DHP) remained statistically significant." (PMID 33776906, 2021). "Of the 26 studies that reported psychological experiences of women with GDM [12,], there appears to be psychological distress associated with concerns related to the baby, blood glucose monitoring and administering insulin injections." (PMID 34308317, 2021). "Insulin therapy, particularly, may be associated with increased psychological distress." (PMID 26817600, 2016). "KEGG pathway analyses revealed additional implicated pathways, including mTOR and insulin signaling, which play a crucial role in cellular growth and metabolism, highlighting the extensive physiological effects of PTSD beyond psychological distress." (PMID 39334086, 2024). "A recent study revealed that use of insulin by T2DM patients may deteriorate their general health condition, induces psychological distress, and associated with activity difficulties in comparison to those using oral agents." (PMID 36817609, 2023). "Others also suggested that the irregular menstrual cycle (oligomenorrhea) or high levels of insulin may lead to increased hunger and psychological distress, which could result in more binge eating." (PMID 35581616, 2022). "Psychological distress was recorded as the major barrier to insulin initiation." (PMID 30993528, 2019). "Until recently, the arsenal of noninsulin antidiabetic agents was not safe to be used in diabetic patients with CKD, and insulin therapy was started early, causing psychological distress to patients and families." (PMID 27471550, 2016). "Since the participants in this study were generally not insulin-dependent, and the initial values of HbA1c were already quite low at baseline, it can be assumed that the psychological distress was not very high and thus offered little room for improvement." (PMID 39349794, 2025). "With regard to the DHP, patients treated with insulin (with or without OHA) scored statistically significantly lower on DHP barriers to activity and DHP psychological distress (i.e., more dysfunction)." (PMID 33776906, 2021).
small cell lung carcinoma (18 papers, 2010 to 2025). Small cell lung cancer (SCLC) is a highly aggressive malignant neoplasm, accounting for 10-15% of lung cancer cases, characterized byrapid growth, and early metastasis. "The differentially expressed genes were affected for small cell lung cancer, axon guidance, Fc gamma R-mediated phagocytosis, MAPK signaling pathway, focal adhesion, insulin resistance, and metabolic pathways." (PMID 31148949, 2019). "Original data indicated reduced growth of small cell lung carcinoma H-69 cells expressing a dominant negative PI3K-C2β upon stimulation with stem cell factor but not with insulin or fibroblast growth factor-2." (PMID 31752944, 2019).
acute myeloid leukemia (17 papers, 2015 to 2025). Acute myeloid leukemia (AML) is a group of neoplasms arising from precursor cells committed to the myeloid cell-line differentiation. "The results demonstrated that SLC3A2 and SLC7A5 were significantly enriched in ribosome, acute myeloid leukemia, insulin signaling pathway, olfactory transduction, etc.." (PMID 40420260, 2025). "The hypermethylated genes were enriched in the insulin signaling pathway (P = 0.0125), spliceosome (P = 0.0219), Notch signaling pathway (P = 0.0259), acute myeloid leukemia (P = 0.0394), and ErbB signaling pathway (P = 0.0467)." (PMID 28072825, 2017). "In addition, ‘PI3K-Akt signaling pathway’42, ‘cell cycle’43, ‘acute myeloid leukemia’44 and ‘Insulin signaling pathway’45 pathways have been experimentally confirmed to be related with TUG1." (PMID 35322118, 2022). "Additionally our pathway analysis using SPIA identified three significant pathways, acute myeloid leukemia pathway, Insulin signaling pathway and mTOR signaling pathway, which are associated with BMD status." (PMID 26390436, 2015). "FIS1 up-regulation decreased cellular ATP levels in anoxic cardiomyocytes and impaired glucose-stimulated insulin secretion in INS-1E cells; and it has been identified as a molecular marker for poor prognosis in patients with acute myeloid leukemia." (PMID 33330472, 2020). "Using computational analysis, we validated the biological significance of these signatures, which were enriched with gene functions in “insulin signaling”, “MAPK signaling”, “acute myeloid leukemia”, “transcription”, “adipogenesis” and “regulation of protein phosphorylation”." (PMID 27752041, 2016). "Insulin and IGF-1 receptors were found expressed on acute lymphoblastic leukemia (ALL) and acute myeloid leukemia (AML) and insulin stimulates in vitro the proliferation of ALL cell lines and primary cells that were sensitive to metformin." (PMID 30147674, 2018).
carbohydrate metabolism disorders (17 papers, 2013 to 2025). "In obese children, the most common primary cause of carbohydrate metabolism disorders is peripheral tissue resistance to insulin action." (PMID 37892696, 2023). "DM is a group of carbohydrate metabolism disorders and is mainly featured by chronic hyperglycemia due to the defects of insulin secretion and/or insulin action." (PMID 36286043, 2022). "Not only the frequency of carbohydrate metabolism disorders was analyzed, but also parameters determining pathogenetic phenomena related to glucose homeostasis - insulin sensitivity (HOMA-IR) and insulin secretion (OGTT, C-peptide - fasting and glucagon stimulated) were examined." (PMID 36589801, 2022). "From these point of view, we may know that insulin might act as a bridge to link both metabolites and carbohydrate metabolism disorder." (PMID 32490246, 2020). "Despite the absence of carbohydrate metabolism disorders in the Gs group of men, fasting serum insulin concentrations were higher in this group compared to subjects from the control group." (PMID 35889836, 2022). "In Poland, carbohydrate metabolism disorders during pregnancy are treated with diet and insulin: oral hypoglycemic agents are not prescribed." (PMID 33008418, 2020).
gastroparesis (17 papers, 2017 to 2026). Paralysis of the muscles of the stomach wall resulting in delayed emptying of the gastric contents into the small intestine. "Some literature puts forth the dysregulation of insulin homeostasis and the loss of physiological response to insulin levels as potential mechanisms of gastroparesis." (PMID 41440963, 2025). "PP glucose profile is particularly unstable in T1DM patients with gastroparesis, who are likely to present a condition of “gastric hypoglycemia” due to a mismatch between exogenous insulin action and the rise in blood glucose." (PMID 31295897, 2019). "The gastric emptying was efficiently improved by insulin treatment, while glycemic control by Voglibose failed in accelerating the gastric emptying, indicating that simple glycemic control was unable to efficiently delay diabetic gastroparesis developing." (PMID 28931726, 2017). "In addition, participants should have well-established insulin correction and carbohydrate-to-insulin factors and no relevant comorbidities (in particular gastroparesis)." (PMID 38194227, 2024). "Classical models of insulin administration to patients without gastroparesis are designed to match postprandial nutrient absorption to short-acting insulin analog pharmacokinetics, which may be inappropriate in diabetic gastroparesis." (PMID 29652893, 2018). "Continuous subcutaneous insulin infusion (CSII) reduced hemoglobin A1c levels by 1.8% and decreased hospitalizations in a study of T1DM patients with gastroparesis, but gastric symptoms were not assessed." (PMID 29652893, 2018).
hyperhomocysteinemia (17 papers, 2010 to 2025). A serious metabolic condition caused by mutations in the MTHFR gene, medications, or nutritional deficiency. "Hyperhomocysteinemia is accused of being responsible for elevating oxidative stress as a result of formation of Hcy thiolactone, which leads to impairment of insulin signaling and causes IR." (PMID 20591133, 2010). "An impairment of Akt activity is observed in the endothelium from insulin-resistant subjects and in hyperhomocysteinemia." (PMID 32794021, 2021). "In addition to its effects on insulin signaling, elevated homocysteine levels (hyperhomocysteinemia) contribute to the formation of neutrophil extracellular traps (NETs)." (PMID 40362226, 2025). "Our results open the door for new hypotheses about the potential benefit of approaching and correcting insulin imbalance and hyperhomocysteinemia in MBI patients." (PMID 38877658, 2024). "Elevated insulin levels can cause the downregulation of CBS and contribute to hyperhomocysteinemia." (PMID 36830912, 2023). "Moreover, we measured other variables that were previously proposed to contribute to hyperhomocysteinemia such as folate, vitamin B12, and insulin levels, as well as alcohol intake." (PMID 32645905, 2020). "In animal studies, insulin affected the activity of enzymes involved in HCY turnover, and hyperhomocysteinemia has been suggested as a possible additional component of MetS." (PMID 30352089, 2018).
Lipedema (17 papers, 2020 to 2026). Disorder of adipose tissue characterized by symmetric and bilateral enlargement of the lower extremities due to abnormal deposition of subcutaneous fat often in obese women. "Higher fasting plasma insulin in our cohort of lipedema patients suggests impaired insulin sensitivity, but in contrast, higher adiponectin plasma concentrations have been associated with improved peripheral and whole-body insulin sensitivity." (PMID 36387874, 2022). "Inclusion criteria were: lipedema, lipoedema, estrogen, estrogen antagonists, female sex hormones, hormones, insulin, puberty, pregnancy, menopause, subcutaneous fat tissue, and subcutaneous adipose connective tissue." (PMID 41575573, 2026). "This context-dependent reprogramming explains why tirzepatide, unlike isolated GIP exposure, produces net reductions in subcutaneous and visceral fat even in insulin-sensitive phenotypes such as early-stage lipedema." (PMID 41226777, 2025). "In female lipedema patients, hemoglobin A1c amounts were lower, and fasting insulin levels were higher compared to their age- and BMI-matched controls." (PMID 40149538, 2025). "Despite elevated BMI, diabetes prevalence is low (5%) and dyslipidemia (7%), with studies showing 48% greater insulin sensitivity in obese lipedema patients." (PMID 41278213, 2025). "This mitochondrial remodeling is particularly relevant for women with lipedema in peri- and postmenopausal stages, where reduced estradiol levels exacerbate visceral fat accumulation, systemic inflammation, and insulin resistance." (PMID 41226777, 2025). "The diet's effects of increasing insulin sensitivity and decreasing inflammation overlap with the pathophysiology of lipedema." (PMID 40419722, 2025). "For lipedema patients, a previous study demonstrated lower glycated hemoglobin A1c (HbA1c) and higher adiponectin levels, despite higher fasting insulin concentrations and higher inflammation and oxidative stress." (PMID 37575263, 2023). "Improvements in liver parameters and glucose tolerance and a decrease in fasting insulin levels were also observed in both study groups, although they were less pronounced in the lipedema group." (PMID 37299581, 2023). "In both groups, TNFα levels positively correlated with insulin concentrations (lipedema: r=0.605; p=0.029; control: r=0.733; p=0.004)." (PMID 36387874, 2022). "However, whole‐body insulin sensitivity was approximately 48% greater (p < 0.05) in the Obese‐LIP group compared to the Obese group, suggesting a relative preservation of insulin sensitivity in women with lipedema." (PMID 40425048, 2025). "Improved insulin sensitivity may play a role in reducing the abnormal fat accumulation seen in lipedema." (PMID 40419722, 2025). "Hence, lipedema patients remain insulin-sensitive, display normal blood pressure and almost normal blood lipid levels, and do not store excess fat in the liver." (PMID 40149538, 2025). "The metabolic alterations induced by nutritional-induced ketosis could potentially lower insulin plasma concentrations sufficiently to facilitate lipolysis of lipedema adipocytes." (PMID 39574523, 2024). "In addition, fasting insulin and adiponectin concentrations were higher in lipedema compared to the control group (p<0.05)." (PMID 36387874, 2022). "We found an unexpected dissociation of lower HbA1c and higher adiponectin in lipedema patients, despite higher fasting insulin concentrations and higher circulating parameters of liver function, inflammation and oxidative stress, compared to age- and BMI-matched women without lipedema." (PMID 36387874, 2022). "Though the stage of lipedema for ADSCs in this study was unknown, these findings seem to align with the fact that the prevalence of diabetes, which relies on insulin sensitivity, is low in lipedema patients." (PMID 36551837, 2022).
Lipedema (continued). "Interestingly in the lipedema group, insulin (r=0.577; p=0.039), TNFα (r=0.741; p=0.004), total cholesterol (r=0.662; p=0.014) and LDL-C concentrations (r=0.693; p= 0.009) were positively associated with age while none of these correlations was significant for the control group." (PMID 36387874, 2022). "Lipedema may represent “healthy” SAT expansion, with lower android-to-gynoid fat ratios and preserved insulin sensitivity compared to body mass index (BMI)-matched controls." (PMID 41278213, 2025). "However, the study did not evaluate changes in glucose–insulin functioning in lipedema patients." (PMID 37299581, 2023). "Although the PPAR-γ activity has been demonstrated to regulate insulin sensitivity, no change in the GLUT4 gene expression was detected in adipocytes differentiated from lipedema ASCs as compared to healthy ASCs." (PMID 32059474, 2020).
metabolism (17 papers, 2011 to 2025). "This increase in TG concentration in serum also induced secretion of cytokines, that is, leptin and IL-6, which are known to have an association with impaired glucose metabolism and insulin sensitivity." (PMID 30319558, 2018). "Adult weight gain primarily reflects the disposition of fat mass with abdominal fat associated with impaired glucose metabolism, increased insulin resistance, and in postmenopausal women, altered estrogen synthesis." (PMID 28003027, 2016). "The prevalence of impaired glucose metabolism escalates in overweight adolescents, even at minimally overweight levels, and is associated with pronounced deterioration of insulin sensitivity." (PMID 24137224, 2013). "It has been consistently reported that circulating levels of BCAAs are high in obese individuals and are associated with worse metabolic disease, which results from inhibiting insulin signaling and impaired glucose metabolism." (PMID 31615057, 2019). "Herein we investigated the effects of low-insulin-response grain products, fatty fish, and berries on glucose metabolism and plasma lipidomic profiles in persons with impaired glucose metabolism." (PMID 21901116, 2011). "Furthermore, hsCRP activates the nuclear factor-κB (NF-κB) pathway, inhibits insulin signalling, and promotes the secretion of pro-inflammatory factors by adipocytes, exacerbating glucose metabolism disorders." (PMID 41357322, 2025). "This study suggests that large-volume resuscitation with isotonic NS in DKA patients is associated with increased ICU length of stay, prolonged insulin infusion, and a higher incidence of non-anion gap metabolic acidosis." (PMID 39981474, 2025). "Therefore, melatonin alleviates glycolipid metabolism disorders by activating the AMPKα/PPARα signaling pathway, reducing lipid deposition in the liver and adipose tissues, and increasing insulin sensitivity." (PMID 33150187, 2020). "Some pediatric studies link higher VDBP levels with higher HOMA-IR or impaired glucose metabolism, suggesting that VDBP may be involved in the vitamin D–insulin axis." (PMID 40943443, 2025). "This study aims to retrospectively evaluate whether large-volume resuscitation with normal saline led to a longer ICU length of stay, overall length of stay, increased time on insulin infusion, and increased incidence of non-anion gap metabolic acidosis after resolution of DKA." (PMID 39981474, 2025).